FGF2 (fibroblast growth factor 2)
Diseases named in the same sentence as FGF2 in open-access papers (continued):
Sharing a sentence is not in itself a finding about the gene and the disease.
breast carcinoma (continued). "Additionally, an ER- breast cancer cell line was shown to maintain paracrine loop signaling from 17β-estradiol and induce the upregulation and secretion of FGF2 and increase FGFR1 signaling." (PMID 33019728, 2020). "Among diverse stimuli, FGF2 expression and secretion can be regulated by estrogens, which act mainly through the classical estrogen receptors (ER)α and ERβ leading to the proliferation, migration and survival of breast cancer cells." (PMID 30866584, 2019). "Likewise, increased FGF2 levels have been observed in plasma samples of patients affected by diverse malignancies, such as leukemia and lung and breast cancers, especially when metastases are present." (PMID 30866584, 2019). "However, the expression of specific FGF2 and VEGF polymorphisms has also been shown to be protective against developing breast cancer." (PMID 31285780, 2019). "FGF2 is hypermethylated in HR+ breast cancers and may have prognosis value 39 while it has low prognosis implication in triple-negative breast cancer." (PMID 31777591, 2019). "As part of ancillary investigations from BETA to evaluate novel mechanisms relating exercise to breast cancer risk, we investigated whether a higher versus a more moderate volume of exercise would lead to differential changes in VEGF and FGF2 levels." (PMID 31285780, 2019). "Moreover, the up-regulation and secretion of FGF2 toward the stimulation of FGFR1 signaling in breast cancers was reported to occur upon estrogen stimulation through the classical ER." (PMID 30866584, 2019). "Since FGFs, in particular FGF2, are under the control of E2 in breast cancer, we examined whether E2 could also be a factor in FGF pathway signaling in NSCLC, which is often positive for ER expression." (PMID 28445992, 2017). "Thus miR-205 binds VEGFA and FGF2 mRNA 3′-UTRs and decreases their expression in breast cancer cells." (PMID 27362808, 2016). "Since cell adhesion is maintained in collectively migrating cancer cells, FGF2 secreted by CD11b+Gr1+ cells may induce adhesion of cancer cells and migration of fibroblasts to enhance collective migration of breast cancer cells." (PMID 25629162, 2015). "In addition to autocrine factors (hepatocyte growth factor or fibroblast growth factor 2), H19 expression is also regulated by estrogen signaling in ERα+ breast cancer cells." (PMID 25944846, 2015). "Also, ARPCA suppresses the angiogenic and tumorigenic potential of prototypic androgen/FGF8b-dependent Shionogi 115 mammary carcinoma cells and of androgen/FGF8b/FGF2-dependent TRAMP-C2 prostate cancer cells." (PMID 25912421, 2015). "ERK pathways control cell proliferation and survival, also in breast cancer cells exposed to FGF2." (PMID 26201468, 2015). "Likewise, 3 μM 194-A effectively suppressed the FGF-2 induced invasion of this two breast cancer cell lines." (PMID 23861711, 2013). "We next investigated whether FGF-2 induces cell migration in the two representative breast cancer cell lines." (PMID 23468877, 2013). "For example, LOX-PP reverts the invasive phenotype of breast cancer cells, inhibits the transformed phenotype of lung and pancreatic cancer cells, interferes with FAK activation in breast cancer cells and inhibits prostate cancer cell growth by targeting FGF-2 cell binding and signalling." (PMID 23750284, 2013). "To better probe into the mechanisms of this progress, we first investigated whether FGF-2 could induce AQP3 expression in human breast cancer cell lines." (PMID 23468877, 2013). "AQP3 is required for FGF-2-induced cell migration in cultured human breast cancer cells." (PMID 23468877, 2013). "In the same line, in the present study, we also found FGF2 to be down-regulated in breast cancer." (PMID 21059268, 2010). "Indeed, FGF-2 was found to be highly up-regulated and exclusively expressed by stromal fibroblasts in breast carcinomas, compared to adjacent normal tissue." (PMID 18232728, 2008). "Consequently, FGF2 presents a paradoxical situation in breast cancer cells." (PMID 39372951, 2024).
breast carcinoma (continued). "EIF4E may be an important regulator of angiogenic factor (such as IL-8 and VEGF) production in breast cancer cells, affecting angiogenesis by regulating the translation of its target mRNAs (VEGF, Cyclin D1 and FGF2), and is associated with a poor prognosis in breast cancer." (PMID 36052258, 2022). "In particular, tamoxifen resistance is associated with enhanced glycolysis in ER-positive breast cancer cells through activation of EGFR/MAPK pathway, a pathway also responsible for ligand-independent Erα activation In the MPA-induced tumor model, the FGF-2/FGFR-2 axis drives HI growth." (PMID 35299741, 2022). "In addition to FGFR1 overexpression, aberrant FGFR signaling in breast cancer may also include the amplification of FGFR1 and FGFR2, activation/mutations of FGFR2, increased secretion of FGF2, and other ligands from tumor microenvironment." (PMID 34831231, 2021). "In addition, focusing on the FGF2/FGFR1 functional interaction that occurs between CAFs and breast cancer cells, we determined that FGF2 secretion by estrogens-treated CAFs prompts the up-regulation of CTGF expression through the FGFR1-ERK1/2-AKT signaling cascade in MDA-MB-231 cells." (PMID 30866584, 2019). "Moreover, on the basis of the present data GPER may be included among the transduction mechanisms involved in the FGF2/FGFR1 paracrine activation that may contribute to breast cancer development." (PMID 30866584, 2019). "However, contrary to these events, FGF-2 inhibits proliferation of ER+ breast cancer cells by activation of cell cycle inhibitors p21WAF1/Cip1, p27KIP1 and p15INK4B resulting in dephosphorylation and activation of retinoblastoma protein (Rb) and cell cycle arrest." (PMID 30119678, 2018). "Thus, when FGF-2 mRNA levels were analysed in a cohort of breast cancer patients, elevated expression of FGF-2 mRNA correlated with a good prognostic outcome, the opposite of the result expected from the naïve perspective that “FGF2 = uncontrolled growth + angiogenesis = cancer”." (PMID 26793421, 2016). "Thus the chemo-sensitizing effect of miR-205 in breast cancer depends on VEGFA/FGF2 downregulation." (PMID 27362808, 2016). "Here, we hypothesized that AQP3 in breast cancer could facilitate FGF-2-induced cell migration." (PMID 23468877, 2013). "First, we tested whether FGF-2 induces AQP3 up-regulation in human breast cancers." (PMID 23468877, 2013). "We suggest that FGF-2 expression may have value as a prognostic indicator in breast cancer." (PMID 9000594, 1997). "Fibroblast Growth Factor 2 (FGF2), a secreted factor within the TME, confers resistance to various therapies in ER+ breast cancer." (PMID 41424847, 2026). "LMWH conjugate LHT7 has inhibited VEGF-dependent phosphorylation in MDA-MB-231 breast cancer cells; LHT7 has also been shown to block other factors such as fibroblast growth factor 2 (FGF2) and platelet-derived growth factor B (PDGF-B)." (PMID 40723905, 2025). "This study highlights the complex interplay between FGF2, DACH1 and the lung microenvironment in influencing the stemness and metastatic behaviour of breast cancer cells." (PMID 38581619, 2024). "The mRNA expression levels for eight pro-angiogenic genes [VEGFA, HGF, FGF1, FGF2, ANGPT1, ANGPT2, PDGFA, and PDGFB] were obtained from the METABRIC (Molecular Taxonomy of Breast Cancer International Consortium) dataset available at cBioPortal public domain." (PMID 39302921, 2024). "FGF2 can activate the ERK1/2 pathway and elevate MYC levels to reduce sensitivity to endocrine therapy and facilitate tumor growth in patients with breast cancer." (PMID 38764020, 2024). "FGF2 is a potent FGF of the epithelial mitogen and is involved in the signaling that is closely related to breast cancer development." (PMID 38674344, 2024). "This activation of the FGF2/FGFR1 signalling pathway promotes self-renewal and pluripotency of breast cancer stem cells." (PMID 40135140, 2024).
breast carcinoma (continued). "Due to the ambiguous role of FGF2 in breast cancer cells, we first employed CRISPR-Cas9 technology to target and knock out FGF2." (PMID 39372951, 2024). "To investigate the role of FGFR1 in the regulation of p21 levels in ER + breast cancer cell lines, we used the pan-FGFR inhibitor TAS-120 (irreversible FGFR1-4 inhibitor) to block the effects of FGF2." (PMID 38553760, 2024). "Surprisingly, compared to ob-aT bASCs, ln-aT bASCs are less efficient in stimulating the proliferation of epithelial-like breast cancer cell lines BT474, MCF7 and MDA-MB-361, defying their secretion of cytokines such as FGF/FGF2, CSF3, CXCL10 and LIF." (PMID 36710348, 2023). "Potential therapeutic inbreast cancer by regulating breast cancer-related genes,including SERPINE1, PGAP3, MAP3K1, MAPK1, GSTO2, VIM, SPARC, and FGF2." (PMID 37191432, 2023). "In multiple ER+ breast cancer cell lines, FGF1 and FGF2 can induce membrane ruffling, which often accompanies metastatic invasion." (PMID 37800138, 2023). "The protein expression of FGF-2, RAD52, RAD50, PBX2, MAP2K2 (MEK2), and S100P was also validated with immunohistochemistry in invasive breast cancer tumor tissues." (PMID 37445737, 2023). "CAFs produce fibroblast growth factor 2 (FGF2), followed up with activation and recruition of ERα and PRBΔ4 to the MYC regulatory sequence leading to the breast cancer growth." (PMID 36721232, 2023). "The present study aimed to analyze the differential expression of genes related to growth factors such as FGF2, FGFBP1, TGFA, TGFBR3, and IGF1R in a radiation- and estrogen-induced experimental breast cancer model." (PMID 36430763, 2022). "Some studies showed that 19,20-EpDPE decreased the growth in a breast cancer murine model and decreased angiogenesis by inhibiting the expression of VEGF-A and Fibroblast Growth Factor 2 (FGF2) in umbilical cord endothelial cells." (PMID 35682855, 2022). "In the context of breast cancer, the expression of FGF5 and FGF6 was detected at very low level in comparison with FGF1 and FGF2." (PMID 35193394, 2022). "The expression of numerous angiogenesis-related proteins was found in breast cancer, including VEGF, Ang-1/Tie-2, PDGF, and bFGF(FGF2)." (PMID 35784750, 2022). "Eight markers (FGF2, IL17B, IP10, MIG, MIP1d, LOX1, OPN and SDC1) found to be upregulated in primary tumours were present in higher concentration in plasma of breast cancer patients." (PMID 34997107, 2022). "We detected the expressed of angiogenesis-related factors in breast cancer cells and found that the mRNA levels of VEGFA and FGF2 were dramatically increased in PCDHB17P overexpression group." (PMID 34350110, 2021). "In lung and breast cancer cell lines resistant to ErbB inhibitors, the increased expression of FGFR1 and/or FGF2 accompanied EMT." (PMID 34830951, 2021). "The results demonstrated that FGF2 modulated resistance to fulvestrant and other PI3K–mTOR pathway inhibitors in anti-oestrogen-resistant ER+ breast cancer." (PMID 34208264, 2021). "In breast cancer, GPC1 is overexpressed and modulates heparin-binding growth factors and FGF2, thus suggesting a role in breast cancer progression." (PMID 33742285, 2021). "Similar to the breast cancer model, anti-VEGF and imatinib combination markedly induced cellular apoptosis in FGF-2+ fibrosarcomas, which otherwise were completely resistant in their monotherapy settings." (PMID 32709869, 2020). "Adipocytokines such as TNF-α, IL-1β, FGF-2, and CCL2 have also been found to be involved in the regulation of LOX expression in breast cancer." (PMID 33123472, 2020). "While SDC4 interaction with α6β4 integrin mediates mammary carcinoma cell migration, downregulation of SDC4 by FGF2-dependent dephosphorylation of FAK promotes the migration of melanoma cells." (PMID 32916872, 2020). "For example, in breast cancer patients, low expression levels of VEGF-A and fibroblast growth factor 2 (FGF2) lead to a better response to neoadjuvant chemotherapy." (PMID 33375067, 2020).
breast carcinoma (continued). "Adipocytokines such as TNF-α, IL-1β, FGF-2, and CCL2, have been found to increase LOX expression in breast cancer." (PMID 33123472, 2020). "Here, we provided novel insights into the ability of estrogens to regulate a feedforward FGF2/FGFR1 activation between the ER-negative CAFs and breast cancer cells." (PMID 30866584, 2019). "Fibroblast growth factor-2 (FGF-2), found abundantly expressed in the bone marrow stroma, has been used to induce dormancy in several breast cancer cell lines." (PMID 30603045, 2018). "In estrogen receptor positive breast cancer, CAF-derived FGF-2 promotes resistance to anti-estrogens which is abrogated with administration of an FGF-2 neutralizing antibody." (PMID 30356656, 2018). "We demonstrated a role for fibroblast growth factor-2 (FGF-2), which is abundant on the marrow stroma extracellular matrix, in the dormancy of ER+ breast cancer cells." (PMID 30119678, 2018). "AZD4547, a pan-FGF inhibitor, is currently being evaluated in AI resistant breast cancer (NCT01791985), because of the link between estrogen and the activation of FGF2." (PMID 28445992, 2017). "Taken together, our data suggest that miR-205 enhances chemosensitivity of breast cancer cells to TAC chemotherapy by suppressing both VEGFA and FGF2, leading to evasion of apoptosis." (PMID 27362808, 2016). "We have recently demonstrated that, fibroblast growth factor 2 (FGFR2), signalling via ribosomal S6 kinase 2 (RSK2), promotes progression of breast cancer (BCa)." (PMID 27852068, 2016). "We further show that miR-205 directly binds VEGFA and FGF2 mRNA 3′-UTRs and confirm that miR-205 levels are negatively correlated with VEGFA and FGF2 mRNA expression in breast cancer patients." (PMID 27362808, 2016). "Here, using chemoresistant breast cancer cell models, we show that miR-205 targets VEGFA as well as FGF2 mRNA 3′-UTR and represses their expression, leading to impaired PI3K/AKT signaling and increased apoptosis both in vitro and in vivo." (PMID 27362808, 2016). "Cancer associated fibroblasts are involved in tumor formation and progression where miR-15 and miR-16 regulate FGF2 and FGFR1 in prostate cancer and miR-18 in breast cancer." (PMID 24597607, 2014). "The results showed that FGF-2 up-regulates AQP3 expression and enhances cell migration in MDA-MB-231 and Bcap-37 breast cancer cells." (PMID 23468877, 2013). "Fibroblast growth factor 2 (FGF-2) contributes to the EMT induction in transformed epithelial cells as a downstream effector of HOXB7, a homeodomain protein which is overexpressed in breast cancer." (PMID 22934011, 2012). "We first examined the modulation of breast cancer cell survival in the presence of IGF-I, IGF-II, FGF-2 or EGF, and we confirmed that, except for EGF, these growth factors promoted MCF-7 and T47D cell survival in vitro under serum-free conditions." (PMID 12838321, 2003). "In this study, we also present evidence for the role of FGF2 in local immunosuppression through demonstrating absence of T-cells and B-cells in FGF2-rich regions in ER+ primary breast cancers." (PMID 40425576, 2025). "To characterize the effects of inhibiting FGFR family members on ER + breast cancer cell growth in 3D cultures, we treated the cell lines with or without FGF2 using various inhibitors." (PMID 38553760, 2024). "This unexpected outcome, particularly in microenvironments with elevated FGF ligand levels, could have detrimental clinical effect in patients, such as ER + breast cancer patients with high FGFR1 and FGF2 expression." (PMID 38553760, 2024). "As expected, silencing YTHDF3 with shRNAs in MCF-7 and MDA-MB-231 breast cancer cells reduced in FGF2 protein levels without affecting its RNA levels." (PMID 39372951, 2024). "Taken together, this data suggested that activation of Fgf2 signaling may decreases DACH1 expression to promote metastatic colonization and stemness/plasticity in breast cancer cells." (PMID 38581619, 2024).
breast carcinoma (continued). "While CAF‐secreted FGF2 has been shown to induce proliferation in breast cancer cell lines, it can be difficult to identify the origin of FGF ligands due to the observation of autocrine FGF signalling in breast cancer." (PMID 37691350, 2023). "Compared with melanoma, breast cancer, hepatocellular carcinoma, squamous cell carcinoma, and lung cancer cell lines, NPC cell lines SUNE-1 and 5-8F showed dramatically high levels of FGF-2, validating the results from clinical NPC samples and the database analysis." (PMID 35439170, 2022). "For example, miR-205, an FGF2- and VEGFA-targeting molecule that negatively regulates their expression, is highly expressed in breast cancer sensitive to TAC (taxol, doxorubicin, cyclophosphamide) chemotherapy, in contrast to drug-resistance cell lines, in which miR-205 is downregulated." (PMID 34830951, 2021). "In addition, a positive correlation between FGF2 and S100A4 levels was assessed in TNBC samples, suggesting their potential cooperation in this aggressive breast cancer subtype." (PMID 33946884, 2021). "Since FGF2 regulates cancer growth and metastasis, including HCC, lung cancer, breast cancer, we used FGF2 as a molecular to confirm the hypothesis." (PMID 34873170, 2021). "Mechanistically, we showed that both knockdown of PTTG1 expression and simvastatin treatment potently attenuated breast cancer cell invasion, presumably through inhibition of the expression of PTTG1 downstream target genes, such as MMP-2, MMP9, c-myc, FGF-2, and cyclin D3." (PMID 33250768, 2020). "Furthermore, breast cancer patients with obesity are less sensitive to anti VEGF treatment and they have increased systemic concentrations of IL-6 and fibroblast growth factor-2 (FGF-2)." (PMID 33339340, 2020). "Upon FGF2/FGFR1 activation, breast cancer cells may acquire invasive phenotype features modulating the expression of cell junction proteins, promoting a spindle-like morphology and increasing cell motility." (PMID 30866584, 2019). "However, as previously reported, metastatic breast cancer cells had high expressions of several other pro-angiogenic factors in addition to VEGF, such as FGF-2, Ang-2 and PDGF-B." (PMID 31164151, 2019). "Therefore, in order to assess the functional FGF2/FGFR1 interplay between CAFs and breast cancer cells, we generated the FGFR1-knockout MDA-MB-231 cells using CRISPR/Cas9 genome editing strategy." (PMID 30866584, 2019). "Thus exogenous VEGFA/FGF2 confers resistance to chemotherapeutics through enhancing PI3K/AKT signaling and inhibiting cell apoptosis in breast cancer cells." (PMID 27362808, 2016). "The tumor media from breast carcinoma and melanoma used in the present study did not influence FGF-2 mRNA regulation." (PMID 25435982, 2015). "Our results by using wound scratch assay confirmed that FGF-2 could increase cell migration in both MDA-MB-231 and Bcap-37 breast cancer cells." (PMID 23468877, 2013). "Indeed, it has been reported that HS produced by malignant breast cancer cells and the HS oligossacharides generated by HPSE1 possess higher fibroblast growth factor 2 (FGF2) and hepatocyte growth factor binding capacity than HS from normal breast cells." (PMID 24083474, 2013). "High FGF2 and/or FGFR2 protein levels have been correlated with high ER levels in breast cancer." (PMID 21767389, 2011). "Despite these constraints, we found a number of biologically meaningful, differentially expressed genes related to HIST1, HIST2 proteins, and some other such as PPARG, FGF2, APOB, CRHBP, CETP, and RXRG in breast cancer tissue compared to corresponding adjacent normal breast tissue." (PMID 21059268, 2010). "Indeed, podoplanin expression can be induced by epidermal growth factor, basic fibroblast growth factor (FGF2) and tumour necrosis factor α in MCF7 breast cancer cells, and by bradykinin in 3T3 fibroblasts." (PMID 17179989, 2007).